EPO (erythropoietin)
Diseases named in the same sentence as EPO in open-access papers (continued):
Sharing a sentence is not in itself a finding about the gene and the disease.
anemia (continued). "Serum erythropoietin levels increased in the HS group and correlated negatively with hemoglobin levels, which suggested that erythropoietin secretion was enhanced by anemia for compensation." (PMID 33328561, 2020). "Furthermore, in the preterm newborn, kidney is immature that cannot produce sufficient amount of erythropoietin level, which results in development of anemia as compared to full-term babies." (PMID 31900190, 2020). "Specifically, the outcomes of EPO expression and anemia symptoms are determined." (PMID 33178327, 2020). "Thus, a control group that received an EPO derivate (asialo-EPO) still suffered from anemia but showed the same beneficial effects on cardiac remodeling." (PMID 32150864, 2020). "Second, some data on EPO were missing, and the association between EPO and renal recovery is not applicable in patients without anemia." (PMID 32311841, 2020). "Therefore, alternative strategies for EPO production in the kidney are promising methods for improving anemia." (PMID 32290638, 2020). "Furthermore, an imbalance between the production of EPO and the demand for EPO is another pivotal reason for anemia in patients treated with ESA." (PMID 32318578, 2020). "Therefore, the repletion of iron stores seems mandatory in the treatment of IDA, and it maximizes the efficacy of EPO-stimulating agents (ESAs), considered a staple in the management of anemia in CKD patients." (PMID 33392212, 2020). "Based on these findings, banking P. falciparum-infected blood could exacerbate preexisting anaemia in blood recipients, through inhibition of erythropoietin activity by high TNF-α levels and low IL-10 levels." (PMID 33195706, 2020). "Therefore, larger interventional studies are required to investigate the effects, including erythropoietin-resistant anemia, of carnitine supplementation for patients undergoing PD." (PMID 32003308, 2020). "In our view, EPO remains an essential medicine to reduce morbidity related to anaemia." (PMID 31468111, 2020). "EPO prognostic value was independent from anemia and mild-to-moderate renal dysfunction." (PMID 33330669, 2020). "Concerning therapeutic interventions, EPO is applied for the treatment of anemia, and colony-stimulating factors are in use for the therapy of neutropenia, while other hematopoietic growth factors still need to demonstrate in vivo clinical relevance before reaching the market." (PMID 32512916, 2020). "The difference in iFGF23 from peak elevated levels to the reduced concentrations following EPO and FG‐4592 treatments could reflect the “iron/anemia sensitive” portion of iFGF23 production during CKD." (PMID 32476270, 2020). "Most of osteosarcoma patients have anemia, which can induce high levels of erythropoietin (EPO)." (PMID 32908942, 2020). "The fact that anemia develops in spite of elevated EPO levels in CKD suggests that peripheral resistance or hyporesponsiveness to EPO may be the factual reason for its occurrence." (PMID 31979104, 2020). "The two primary FDA approved indications for the use of EPO stimulating agents are anemia secondary to chronic kidney disease and chemotherapy-induced anemia in patients with cancer, and generally limited to those with hemoglobin less than 10 g/dL due to the risk of adverse effects." (PMID 33138778, 2020). "In severe renal dysfunction, insufficient erythropoietin will aggravate anemia, speed up heart rate compensation, strengthen myocardial contractility, activate sympathetic nerves, constrict pulmonary vessels, increase pulmonary artery pressure, and consequently aggravate cardiac remodeling." (PMID 32793638, 2020). "In addition to promoting the production of EPO, clinical trials have shown that it can significantly reduce hepcidin and can potentially be used for the treatment of inflammation-induced anemia in CKD." (PMID 32850902, 2020).
anemia (continued). "The current study revealed that BM caused anemia manifested by significant decreases in values of RBCs, Hb, and PCV and that it could be erythropoietin-resistant anemia due to oxidative stress." (PMID 33114212, 2020). "It suggests that variations in shear-stress determinants and blood viscosity, including anemia and hemoconcentration arisen by the dialysis or erythropoietin (EpO) supplementation, may affect the vesiculation rate in the endothelium." (PMID 32351956, 2020). "Postoperative use of rHu-EPO and iron supplementation could improve the anemia-related parameters and reduce the requirement for ABT after THA without increasing the risk of VTE in the short term." (PMID 33213494, 2020). "Increased levels of EPO were found in smokers despite higher Hgb levels, suggesting that the condition of anemia in smokers may be masked by high Hgb levels." (PMID 33456476, 2020). "Central to the current discussion of anemia management with EPO and biosimilar drugs is the identification of those patients that respond normally to pharmacologic concentrations of EPO or erythropoiesis stimulating agents (ESAs) and those patients that do not." (PMID 33214633, 2020). "As the utility of oral iron is limited due to short wait times (29 days) until surgery, and the use of erythropoietin stimulating agents is discouraged due to thrombosis and malignancy concerns, IV iron is often the only choice for the treatment of pre-operative anemia in HPB patients." (PMID 32346397, 2020). "Erythroid deletion of SETD8, achieved by crossing mice that harbor floxed Setd8 alleles with mice that that express cre-recombinase under the direction of the endogenous erythropoietin promoter, is embryonic lethal by embryonic day 11.5 (E11.5) due to profound anemia." (PMID 32178723, 2020). "The anemia of chronic kidney disease and ESKD may be associated with failed EPO production, diminished sensitivity to exogenous EPO or compounding effects of dysregulated trace metal metabolism." (PMID 33214633, 2020). "Anemia is associated with the increased risk of cognitive decline and dementia in the general population and ESRD patients, which can be improved after anemia treatment with erythropoietin." (PMID 33304233, 2020). "Fourthly, considering a higher dosage of ESA related risk of CV events and HIF-PHIs only increase EPO in the physiological level, whether the target Hb level could be upregulated with HIF-PHIs treatment for anemia treatment is yet to be studied." (PMID 32869703, 2020). "However, there is not always a clear inverse correlation between the degree of anemia and EPO levels in the serum." (PMID 33143240, 2020). "Recombinant human EPO (rhEPO) is currently used as a therapy to treat anemia related to CKD." (PMID 32982979, 2020). "Deficiency of erythropoietin or a lack of sensitivity to its target tissue is one of the development mechanisms of chronic diseases anemia." (PMID 32560029, 2020). "It has been reported that there may be insufficient secretion of EPO in patients with chronic disease anemia." (PMID 32848738, 2020). "It is noted that EPO mediates the expansion, survival, and differentiation of CFU-E and erythroid committed precursors while the genetic mutations in EPO or the EPO receptor gene lead to embryonic lethality with severe anemia." (PMID 31467565, 2019). "Indeed, erythropoiesis participates in systemic iron homeostasis by regulating hepcidin, which is upregulated in response to iron overload and inflammation and downregulated by erythropoietic stimuli such as anemia, hypoxia, and EPO synthesis/administration." (PMID 30834265, 2019). "Anemia is due to the impairment of the renal endocrine role in ESRD patients, the renal secretion of erythropoietin (EPO) causes red blood cell (RBC) proliferation in a healthy human, but EPO is insufficiently produced in ESRD patients, which leads to decreased RBC production or hemoglobin." (PMID 31217925, 2019).
anemia (continued). "We speculated that enhancement of EPO production by anemia and hypoxemia might overwhelm inhibition of EPO production by inflammation in patients with sepsis." (PMID 31183575, 2019). "Moreover, inflammation contributes to the progression of CKD, insulin resistance, oxidative stress, endothelial dysfunction, mineral and bone disease, anemia and erythropoietin (Epo) resistance." (PMID 31906008, 2019). "Mechanistically, anemia is directly involved with increased levels of IL-6 and reveals an inverse relationship between hemoglobin and IL-6 in frail patients, with elevated levels of IL-6 directly inhibiting erythropoietin or interfering with iron metabolism." (PMID 31533354, 2019). "Insight in the activity of the EPO-FGF23 signaling pathway in rare hereditary anemias with varies degrees of hemolysis and ineffective erythropoiesis and varying circulating EPO concentrations, will add to the understanding of the pathophysiology and bone complications of these diseases." (PMID 30971944, 2019). "erythropoietin, red cell transfusions and steroids to correct anaemia." (PMID 31888683, 2019). "The dose requirement of EPO by the sc route was 22% lesser than that by the IV route; however, DA-α has similar dose requirements by both the sc and IV routes, which simplifies management of anemia." (PMID 30866856, 2019). "ACD, therefore, is caused by a complex interplay of proinflammatory cytokines which induce dysregulation in iron homeostasis, erythroid progenitor cell differentiation, erythropoietin synthesis and red cell longevity, all culminating in the pathogenesis of anemia." (PMID 31614529, 2019). "However, the finding suggests that the increased production of EPO is unable to resolve the anaemia, possibly due to the initiation of apoptosis of nascent erythroid cells." (PMID 30894794, 2019). "Nutritional therapy is also useful in reducing the quantity and use of drugs in CKD patients, such as antihypertensive drugs, phosphate binders (to prevent secondary hyperparathyroidism and vascular calcification), erythropoietin (to treat anemia) and diuretics (to reduce edema)." (PMID 31906008, 2019). "In addition to promoting red blood cell formation and correction of anemia, EPO can protect cardiomyocytes against ischemic injury and induce NO production by endothelial cells, thereby improving microvascular function." (PMID 31551803, 2019). "In MDS, correlation analysis of the relationship between endogenous EPO levels and erythroid progenitors indicated that the development of anemia is not caused by an abnormality in the capacity of EPO to induce the generation of CFU-E." (PMID 31394818, 2019). "These suggest that anti-EPO antibodies may play a significant role in malaria and malaria-related anaemia." (PMID 30894794, 2019). "In addition, anemia is a common complication in patients with chronic renal failure and hematopoietic agents such as erythropoietin-stimulating agents (ESAs) are frequently used for treatment." (PMID 31754187, 2019). "They evaluated anti-EPO in relation to the pathogenesis of malaria-related anaemia in different strains of semi-immune mice infected with Plasmodium berghei and established that malaria infection was associated with anti-EPO antibody production in some strains of mice." (PMID 30894794, 2019). "Also, in curing anaemia of renal origin, EPO given intravenously had positive effects on macular oedema, improved visual acuity in patients with DR and also led to the reduction of exudative maculopathy and proliferative changes of the disease." (PMID 31727007, 2019). "We recruited participants with T2D as these people may develop hypoxic cases such as anemia, given that EPO level is very crucial in such conditions." (PMID 31139640, 2019). "Therefore, larger interventional studies are required to investigate the effects of carnitine supplementation for erythropoietin-resistant anemia in patients on PD." (PMID 31689941, 2019).
anemia (continued). "Moreover, a mild hyperparathyroidism was documented and subcutaneous erythropoietin (EPO) administration was started to treat a progressive anemia." (PMID 30791938, 2019). "Therefore, anaemia correction by erythropoietin and/or iron replenishing therapy is an integral component in the management of anaemia of CKD." (PMID 31640237, 2019). "In addition, anemia can be considered a pro-inflammatory state, arising in part from a defect in the normal compensatory production of erythropoietin in response to a declining hemoglobin concentration." (PMID 30875895, 2019). "Treatment of this disease primarily involves treatment of anemia with transfusions, erythropoietin (EPO) or granulocyte colony stimulating factor (GCSF), and replacement of pancreatic enzymes has been reported in patients with exocrine pancreatic insufficiency." (PMID 31083569, 2019). "Interestingly, 43% of patients without renal insufficiency (RI) and 85% of patients with renal insufficiency had inadequate EPO responses to anaemia." (PMID 31683939, 2019). "Furthermore, our previous study noted that the prevalence of anemia decreased, and patients with anemia showed increased erythropoietin after TRT." (PMID 30736442, 2019). "However, we applied aDCSI, history of antidiabetic agent use as diabetes severity markers, erythropoietin (EPO) use, and anemia percentage as CKD severity markers." (PMID 31112536, 2019). "EPO increases the synthesis of erythrocytes in the bone marrow and this leads to a depletion of iron stores and the reduced availability of iron contributes to anemia in CKD." (PMID 31614529, 2019). "We outline its importance for red blood cell production, which might add, among others, to the understanding of bone marrow responses to endogenous erythropoietin in rare hereditary anemias." (PMID 30971944, 2019). "While patients with renal failure clearly benefit from EPO treatment to correct anemia several clinical trials of EPO treatment to normalize hemoglobin values in kidney disease showed increase cardiovascular morbidity and mortality associated with high dose EPO treatment." (PMID 32038269, 2019). "Premature infants may have anemia due to multiple factors, such as rapid body growth, low plasma levels of erythropoietin, or inadequate nutrient intake, among others." (PMID 31590415, 2019). "Androgen therapy also has potential to treat anemia of CKD in hypogonadal men as an adjunct to EPO." (PMID 31798530, 2019). "For Hb levels ≥ 10 g/dL, however, the anemia can be managed with IV iron alone without the risk of achieving supraphysiological levels of Hb given the limited supply of erythropoietin in these patients." (PMID 30614439, 2019). "Several reports have shown that hypothyroidism may contribute to erythropoietin resistance in chronic hemodialysis patients and that early thyroxine administration can improve anemia significantly." (PMID 31015507, 2019). "β-thalassemia intermedia mice are characterized by anemia, iron overload and high endogenous EPO." (PMID 30971944, 2019). "Treatment with exogenous EPO, e.g., rHuEPO, can correct anemia in many with CKD." (PMID 31600973, 2019). "Inflammatory cytokines may affect the development of anemia through suppression of bone marrow erythropoiesis, suppression of erythropoietin production, or interfering with the iron status." (PMID 31521117, 2019). "Liver can also produce EPO to promote erythropoiesis in an oxygen-dependent mode, but it is not sufficient to compensate the loss of kidney EPO in end-stage renal disease, leading to anemia that requires systemic treatment with recombinant EPO." (PMID 30823476, 2019). "Study found that erythropoietin could help treat tumor-related anemia and improve anemia and sleep quality of patient." (PMID 31531357, 2019). "Treatment with exogenous erythropoietin (EPO) can correct anemia in many with CKD." (PMID 31600973, 2019).
anemia (continued). "These multi-tissue responses underscore the pleiotropic potential of the EPO response and may contribute to various physiological manifestations accompanying anemia or ischemic response and pharmacological uses of EPO." (PMID 32038269, 2019). "Mice that lack EPO or its receptor die in utero at day 13.5 due to severe anemia." (PMID 32038269, 2019). "Erythropoietin levels are highly elevated in response to severe anemia." (PMID 31792345, 2019). "We treated this anemia by erythropoietin (EPO) 250 U/kg three times per week." (PMID 31223410, 2019). "Additionally, these data indicate that small numbers of ON-REP cells are sufficient for recovery from anemia because EPO-production levels in each ON-REP cell are very high." (PMID 31798631, 2019). "Correction of anemia with erythropoietin (25–50 units/kg, subcutaneous, 3 times a week) and iron supplements may be beneficial in patients with nOH." (PMID 31452021, 2019). "Researchers found that LPS-induced renal inflammation in mice can increase the miR-122 levels in the blood and decrease the EPO expression in the kidney, which may be one of the mechanisms of inflammation that induce anemia." (PMID 31915448, 2019). "Anemia may be managed by ensuring the proper metabolism of iron and with the administration of erythropoietin; blood transfusions may be performed in selected cases." (PMID 30048562, 2019). "Our results should encourage clinicians to assess EPO levels in diabetic patients with anemia." (PMID 31619722, 2019). "Treatment may include nutritional supplementation such as with iron, or Erythropoietin where there is anaemia of chronic disease." (PMID 31674904, 2019). "Third, the causes of anemia vary, but KNHANES does not include information such as erythropoietin level, iron state, or vitamin B12 level, which can be used to identify the cause of anemia." (PMID 31836793, 2019). "To examine this combined regulation, we administered four doses of EPO to mice kept for six weeks since weaning on an iron deficient diet; this pretreatment decreased the mean cell volume, but did not yet cause iron deficiency anemia." (PMID 30958854, 2019). "Aiming at anemia correction, administering recombinant human EPO (rHuEPO) could improve patients' hemoglobin (Hb) levels and exert substantial clinical benefits." (PMID 30915348, 2019). "If patients present with anemia, the measurement of serum erythropoietin as well as markers of iron metabolism, such as serum iron and ferritin, is necessary for reaching a diagnosis and treating renal anemia using appropriate erythropoiesis stimulating agents." (PMID 30684957, 2019). "Inhibiting these restraining mechanisms could provide alternative approaches to treat anemia in an EPO-independent fashion." (PMID 30158520, 2018). "The underlying mechanism that might partly be the facilitation of spontaneous platelet aggregation by EPO used to treat anemia and its interaction with blood coagulation factors, both leading to tendency of thrombosis." (PMID 30741617, 2018). "Compared to blood loss, anemia in young CKD rats is associated with inappropriate responses in the HIF-EPO-EPO-R axis: kidney HIF2α and renal EPO are not increased, BM and bone EPOR levels, as well as bone pSTAT5 response to EPO are reduced." (PMID 29738538, 2018). "Erythropoietin (EPO) stimulates erythropoiesis and is commonly used to treat anemia." (PMID 30158520, 2018). "This possibly could have been precipitated by treatment with erythropoietin for pre- and postoperative anemia." (PMID 29429414, 2018). "Based on these observations, we hypothesize that ASP ameliorates anemia of CKD by stimulating EPO production, suppressing hepcidin, and attenuating inflammation." (PMID 30108502, 2018). "This could be accelerated in the presence of concomitant treatment with erythropoietin-stimulating factor for anemia." (PMID 29429414, 2018).